GAD2 (glutamate decarboxylase 2)
Diseases named in the same sentence as GAD2 in open-access papers (continued):
Sharing a sentence is not in itself a finding about the gene and the disease.
schizophrenia (30 papers, 2011 to 2026). A major psychotic disorder characterized by abnormalities in the perception or expression of reality. "Regardless, there appears to be diagnostic variation for alternative GAD2 transcripts in schizophrenia and affective disorders." (PMID 26848839, 2016). "Interestingly, GAD2 knockout mice exhibit deficits in prepulse inhibition, an abnormality involving defective modulation of the startle reflex, also associated with schizophrenia." (PMID 26848839, 2016). "GABAergic dysfunction in schizophrenia and mood disorders was reflected by decreased levels of GAD2." (PMID 34306154, 2021). "Two genes, GAD1 and GAD2, control GABA synthesis, but only the former has been clearly implicated in schizophrenia." (PMID 26848839, 2016). "Another group has reported that GAD2 full length protein expression was decreased in the primary auditory cortex and cerebellum of schizophrenia patients and cerebellum of bipolar disorder patients." (PMID 26848839, 2016). "Compared the expression of GAD2 transcripts in dorsolateral prefrontal cortex (DLPFC) of patients with schizophrenia, affective disorders and normal controls." (PMID 26848839, 2016). "The subjects with schizophrenia and completed suicide (p = 2.73E-03) or positive nicotine exposure (p = 1.87E-03) showed significantly higher expression of GAD2 full length transcript compared with natural deaths or nicotine free patients with schizophrenia." (PMID 26848839, 2016). "The correlation between GAD2 full length and nicotine is intriguing and suggests a previously unrecognized role for nicotine in cortical function in schizophrenia." (PMID 26848839, 2016). "In prefrontal cortex (PFC), GAD2 expression has been reported as decreased, increased and normal in patients with schizophrenia." (PMID 26848839, 2016). "The schizophrenia patients with nicotine exposure had increased expression of GAD2 full length transcript in the DLPFC comparing to nicotine-free patients with schizophrenia." (PMID 26848839, 2016). "We observed the up-regulated expression of GAD2 full length transcript in patients with schizophrenia who are suicides." (PMID 26848839, 2016). "The full length GAD2 mRNA was significantly decreased in expression in the DLPFC of patients with schizophrenia and bipolar disorder compared with controls." (PMID 26848839, 2016). "The expression of GAD2 full length transcript is decreased in the DLPFC of schizophrenia and bipolar disorder patients, while GAD2 truncated transcript is increased in bipolar disorder patients but decreased in schizophrenia patients." (PMID 26848839, 2016). "A secondary network analysis of significantly altered focus and reference proteins associated the IL-1 receptor with SERPINA3, GABRG2, GAD2, and IRAK1 with schizophrenia and related disorders (early-onset schizophrenia, schizoaffective disorder, and psychosis)." (PMID 33976392, 2021). "Post-hoc analyses revealed that the expression of GAD2 full length was significantly decreased in schizophrenia patients (24% decrease, p = 7.05E-10) and bipolar disorder patients (22% decrease, p = 1.28E-02), with no changes in MDD patients (p = 5.92E-02) compared with controls." (PMID 26848839, 2016). "Moreover, the patients with schizophrenia with completed suicide or positive nicotine exposure showed significantly higher expression of GAD2 full length transcript." (PMID 26848839, 2016). "In general, the findings presented here confirm that splice variants of GAD2 are expressed differently in the human DLPFC across normal brain development and that these two transcripts may be involved in the pathophysiology of schizophrenia and affective disorders." (PMID 26848839, 2016). "Alternative transcripts of GAD2 may be important in the growth and development of GABA-synthesizing neurons as well as abnormal GABA signaling in the DLPFC of patients with schizophrenia and affective disorders." (PMID 26848839, 2016).
schizophrenia (continued). "Studies of GAD2 in postmortem brains of patients with schizophrenia have been inconsistent and mostly negative." (PMID 26848839, 2016). "While a decrease in full length GAD2 mRNA expression in bipolar disorder has been previously reported in the hippocampus, this same group did not see an effect in schizophrenia." (PMID 26848839, 2016). "No consistent changes in GAD2 expression have been found in brains from patients with schizophrenia." (PMID 26848839, 2016). "Additionally, an increase in GAD2 expression may also be responsible for the observed increase in GABA levels in animal models and schizophrenia patients treated with typical antipsychotic drugs." (PMID 37803004, 2023).
type 2 diabetes (18 papers, 2014 to 2026). "Based on an analysis of the evolutionary history of candidate genes, we showed that common 5′ variants in CDKAL1, CYB5R4, GAD2, and PPARG as well as an intronic type 2 diabetes-associated CDKAL1 variant exhibit non-neutral evolutionary patterns." (PMID 25222615, 2014).
Cognitive impairment (16 papers, 2016 to 2026). Abnormal cognition is characterized by deficits in thinking, reasoning, or remembering. "SCZ patients exhibited defective expression of histone H3K4-trimethylation (H3K4me3) and GABAergic promoter subsets of genes (GAD1, GAD2, NPY, and SST) in the prefrontal cortex, all of which are strongly associated with cognitive impairment." (PMID 36406755, 2022). "In contrast, diffuse plaques in Gad2-APP mice accumulated comparable levels of Aβ over time but failed to elicit a significant cellular response or cognitive impairment." (PMID 41495836, 2026). "The genes of cognitive impairment modified by histone include GAD1, GAD2, NMDAR, CACNA1H, and BDNF." (PMID 36406755, 2022).
autism (12 papers, 2011 to 2025). Persistent deficits in social interaction and communication and interaction as well as a markedly restricted repertoire of activity and interest as well as repetitive patterns of behavior. "In prior studies, GAD1 and GAD2 have been shown to be reduced in parietal and cerebellar cortex in autism and GABA receptor density is reduced in post-mortem autism cerebral cortex." (PMID 29859039, 2018).
Obesity (9 papers, 2005 to 2023). Accumulation of substantial excess body fat. "The GAD2 polymorphism has been reported to be associated with eating behaviors among women and the risk of obesity." (PMID 34572079, 2021). "Next, we designed and unilaterally injected AAV-hSyn-DIO-Cacna2d1-pA and AAV-hSyn-DIO-eGFP (1:1) into the right-lateral region of the vlPAG of DIO Gad2-Cre mice to overexpress CACNA2D1 in HFD-induced obesity mice." (PMID 37910621, 2023). "Earlier studies have shown that polymorphisms of GAD2, which encodes an enzyme that catalyzes the production of gamma-aminobutyric acid (GABA), are associated with obesity, BMI, and postabsorptive resting energy expenditure in selected populations." (PMID 25222615, 2014). "Although this example raises questions concerning the role of GAD2 in obesity, it would be premature to discount GAD2's involvement entirely." (PMID 17196040, 2006). "To test whether departure from HWE is specific to CART, we reanalyzed previous genotyping data obtained in the 368 controls for eight genes, some of them associated with obesity or associated phenotypes such as UCP3, APM1, PGC1 and GAD2 genes." (PMID 15823203, 2005). "With the exception of GAD2 variant rs2236418, none of the candidate variants had been implicated in earlier GWA studies although CDKAL1, CYB5R4, and PPARG loci have been associated with diabetes- and/or obesity-related traits." (PMID 25222615, 2014).
thymoma (7 papers, 2017 to 2026). A neoplasm arising from the epithelial cells of the thymus. "The characteristic members of this group are GIF, CYP2A7, LCN1, as well as GAD2, the expression of which followed AIRE’s expression pattern in thymomas, and conceivably CT-As, for which AIRE-dependency in human thymus remains unknown." (PMID 28861084, 2017).
COVID-19 (6 papers, 2022 to 2023). A disease caused by infection with severe acute respiratory syndrome coronavirus 2. "Five hub genes, including GAD2, SST, TAGLN3, SYP, and KCNJ4, were further verified using the test_datasets of COVID-19, AD, and PD." (PMID 36902271, 2023).
Parkinsonism (6 papers, 2020 to 2025). Characteristic neurologic anomaly resulting from degeneration of dopamine-generating cells in the substantia nigra, a region of the midbrain, characterized clinically by shaking, rigidity, slowness of movement and difficulty with walking and gait. "However, Gad2+ neurons uniquely showed upregulation of protein glycosylation-related gene sets (CS = 1.5) and ATP synthesis (CS = 1), oxidative phosphorylation (CS = 5.5), and Parkinson’s disease pathway (CS = 1), suggesting an increase of mitochondrial function in these neurons." (PMID 36670467, 2023).
Alzheimer disease (5 papers, 2021 to 2025). A progressive, neurodegenerative disease characterized by loss of function and death of nerve cells in several areas of the brain leading to loss of cognitive function such as memory and language.
anxiety disorder (4 papers, 2013 to 2022). A category of psychiatric disorders which are characterized by anxious feelings or fear often accompanied by physical symptoms associated with anxiety. "The large ongoing GWAS studies should inform whether GAD2 variants predispose to various anxiety disorders or other psychiatric phenotypes." (PMID 23659354, 2013). "Second, it was unclear why the results of this study (low PLR and high NLR of the GAD-7 and GAD-2 in detecting anxiety disorders) differed from those of previous study." (PMID 30936840, 2019). "After adjusting for weights, an estimated 1125 (13%, 95% CI 10% to 18%) of GAD-2 (<3) negatives and 404 (36%, 95% CI 23% to 51%) of GAD-2 (≥3) positives met criteria for any SCID anxiety disorder (including PTSD and OCD)." (PMID 30185582, 2018). "The GAD-7 and GAD-2 have also been widely utilized to screen for other anxiety disorders; however, their diagnostic utility has not been fully justified with empirical support, especially in East Asian samples." (PMID 30936840, 2019). "GAD2 has been studied as a candidate gene for anxiety disorders in two larger subsequent studies." (PMID 23659354, 2013). "We also investigated whether the GAD-7 and GAD-2 could be used to detect any anxiety disorder." (PMID 30936840, 2019). "GAD2 is an enzyme involved in the gamma-aminobutyric acid (GABA) synthesis, and is therefore an intriguing candidate gene as abnormalities in the GABA system have been observed in anxiety disorders." (PMID 23659354, 2013).
autoimmune polyendocrine syndrome (4 papers, 2020 to 2025). "GAD2 is a glutamate decarboxylase 2 coding gene, diseases associated with GAD2 include autoimmune polyendocrine syndrome and stiff‐person syndrome, among its related pathways are neurotransmitter release cycle and database." (PMID 32508047, 2020).
Hypoglycemia (4 papers, 2017 to 2025). A decreased concentration of glucose in the blood. "GAD1 mRNA levels in this cell population were unaffected by hypoglycemia, whereas GAD2 gene expression was inhibited." (PMID 38902332, 2024). "The direction of SF-1 regulation of GAD2 transcription profiles is evidently dependent upon glucose status, as this control shifts from stimulatory-to-inhibitory during eu- versus hypoglycemia; elucidation of the mechanisms that mediate this directional switch will require further investigation." (PMID 39024550, 2024). "Notably, baseline ratios of GAD2 versus GAD1 transcript profiles varied between the two divisions, and were affected by hypoglycemia in each site, as this ratio increased in VMNdm neurons, but declined in VMNvl cell samples." (PMID 38902332, 2024).
viral infection (4 papers, 2019 to 2023). "Gad2-ires-Cre, Rosa26-lsl-L10GFP mice were injected in the area postrema with an AAV containing a Cre-dependent ChR2-mCherry allele (AAV-Flex-ChR2-mCherry); post hoc histological analysis confirmed that viral infection was largely restricted to the area postrema." (PMID 35705049, 2022). "To determine how fast AAV-Cacna2d1 viral infection can increase the expression level of CACNA2D1 in DIO mice, we explored the mRNA levels of Cacna2d1 1 day and 3 days after bilaterally injecting AAV-DIO-Cacna2d1 into the vlPAG brain region of DIO Gad2-Cre mice by RNA scope." (PMID 37910621, 2023). "Rabies virus infection was clearly detectable at the injection site in GAD2-IRES-Cre mice compared with wild-type littermates, indicating no leakage of viral infection." (PMID 31068780, 2019).
status epilepticus (3 papers, 2021 to 2025). Status epilepticus is defined as a continuous seizure lasting more than 30 min, or two or more seizures without full recovery of consciousness between any of them. "For example, the metabolite most enriched in Gad2-Fgf13 cKO brains was L-kynurenine (Log2fold change = 2.58, p=0.0009), a metabolite most enriched in patients with status epilepticus." (PMID 39773461, 2025). "Metabolite set enrichment analysis in Gad2-Fgf13 cKO vs. WT revealed that the most enriched Kyoto Encyclopedia of Genes and Genomes (KEGG) pathway among upregulated metabolites was glycolysis (p=4.29E-6), also consistent with data obtained in patients in status epilepticus." (PMID 39773461, 2025).
cocaine addicts (2 papers, 2012 to 2013). "Changes specific to cocaine addiction were the down-regulation of GAD1 and GAD2, genes that encode glutamic acid decarboxylase, the enzyme responsible for the majority of GABA synthesis from glutamate in the CNS." (PMID 22253714, 2012). "Factor 6: GABA synthesis; GAD2: GAD2 showed expression changes in alcoholics/cocaine addicts." (PMID 23717525, 2013).
Tinnitus (2 papers, 2022 to 2024). Tinnitus is an auditory perception that can be described as the experience of sound, in the ear or in the head, in the absence of external acoustic stimulation. "Cre-dependent excitatory hM3Dq virus was used to selectively excite the aTRN of Gad2-Cre mice, in which systemic administration of sodium salicylate was used to induce tinnitus." (PMID 38629053, 2024). "Secondly, we only verified salicylate-induced tinnitus-like behavior in wild-type mice and did not assess this in Gad2-Cre mice, in which the modulatory effects of aTRN on tinnitus were examined in the current study." (PMID 38629053, 2024).
Anosmia (1 paper, 2022). An inability to perceive odors. "We have identified a gene regulatory network, Gsx1/2 – Dlx1/2/5/6 – GAD2/1/Sp8/Sp9 – Tshz1 – Prokr2, which governs OBiN development; mutations of some of these genes result in human Kallmann syndrome with abnormal olfactory function (anosmia or hyposmia)." (PMID 34374948, 2022).
cataract (1 paper, 2025). Partial or complete opacity of the crystalline lens of one or both eyes that decreases visual acuity and eventually results in blindness. "Notably, these findings contrast with previous research where GAD-1 (Feeling nervous, anxious, or on edge) demonstrated the highest centrality value, and studies of cataract patients that recognized GAD-2 as central but did not identify GAD-4 as significant." (PMID 41050802, 2025).
HIV encephalitis (1 paper, 2016). "When HIV-positive subjects were sorted according to whether or not they had HIV encephalitis (HIVE) at autopsy, the mRNAs were significantly lower than HIV-negatives in the patients without and with HIVE both (by 26 and 23 % for GAD1, 21 and 27 % for GAD2, 20 and 24 % for GJD2)." (PMID 26829944, 2016).
Hyperhidrosis (1 paper, 2024). Abnormal excessive perspiration (sweating) despite the lack of appropriate stimuli like hot and humid weather. "Individuals with axillary hyperhidrosis had high GAD-2 mean points (p = 0.02)." (PMID 38283646, 2024).
Leigh syndrome (1 paper, 2019). A progressive neurological disease defined by specific neuropathological features associating brainstem and basal ganglia lesions. "In contrast, Vglut2:Ndufs4cKO and Gad2:Ndufs4cKO mice had reduced lifespan and body weight, which was accompanied by a decrease in food intake, which are common clinical signs that appear in Leigh Syndrome patients." (PMID 31403401, 2019).
lung adenocarcinoma (1 paper, 2013). A carcinoma that arises from the lung and is characterized by the presence of malignant glandular epithelial cells. "We have observed that GAD1 is up-regulated in three out six cancer types under study, namely colon, liver and lung adenocarcinoma, and GAD2 is up-regulated in prostate cancer." (PMID 23967163, 2013).
mesenchymal tumors (1 paper, 2017). "All three GABA related genes -- glutamate decarboxylase 1 (GAD1) and 2 (GAD2) and 4-aminobutyrate aminotransferase (ABAT) -- were lower in mesenchymal tumors, which in contrast showed higher IDO1 (indoleamine 2, 3-dioxygenase 1) and TDO2 (tryptophan 2, 3-diaxygenase)." (PMID 28245795, 2017).
nicotine dependence (1 paper, 2023). Physical and psychological dependence on nicotine.
omphalocele (1 paper, 2023). Omphalocele is an embryopathy classified in the group of abdominal celosomias and is characterized by a large hernia of the abdominal wall, centered on the umbilical cord, in which the protruding viscera are protected by a sac. "In agreement, rats with a deletion of the gene encoding GAD65 (Gad2) or the gene encoding GAD67 (Gad1), leads to GABA reduction and palate deformation, while double GAD65/GAD67 knockout mice exhibit an increased chance of cleft palate, omphalocele and abnormal spine curvature (kyphosis)." (PMID 37108127, 2023).
pyridoxine-dependent epilepsy (1 paper, 2004). A rare neurometabolic disease characterized by recurrent intractable seizures in the prenatal, neonatal and postnatal period that are resistant to anti-epileptic drugs (AEDs) but that are responsive to pharmacological dosages of pyridoxine (vitamin B6). "Linkage of pyridoxine-dependent epilepsy has however been reported to 5q31.2-31.3, with GAD1 and GAD2 excluded." (PMID 15571623, 2004).
retinal ischemia (1 paper, 2018). A ischemic disease that involves the retina. "The downregulation of GAD1 and GAD2 may be associated with ischemic processes as decreased levels of GAD1 and GAD2 have previously been observed with retinal ischemia." (PMID 30366444, 2018).
thyroid cancer (1 paper, 2024). "We found multiple instances of glutamate receptors (e.g., GRM1, 2, 4, 5) and glutamate decarboxylase 1 and 2 (GAD1, 2), with the axes of GAD2 with GRM1, 4 and 5 being always significantly associated with lower survival in endometrium and thyroid cancer tissues." (PMID 38723607, 2024).
cancer (17 papers, 2013 to 2025). A tumor composed of atypical neoplastic, often pleomorphic cells that invade other tissues. "The enzymatic functions of GAD1 and GAD2 are almost similar; however, their functions remain unclear in cancer tissues." (PMID 24261884, 2013). "For instance, the GAD2, AOC2 and DPYS had the hypermethylation in more than most of human cancers; on the contrary, most of βAMRGs showed the hypomethylation in more than most of human cancers." (PMID 38637116, 2024).